E2F1 (E2F transcription factor 1)
Diseases named in the same sentence as E2F1 in open-access papers (continued):
Sharing a sentence is not in itself a finding about the gene and the disease.
tumor (continued). "Notably, chromatin regulators Hells and Uhrf1 were identified to be expressed in murine RB tumors, but their expression was abrogated in E2f1 or E2f3‐deficient background in the same murine RB model with a concomitant rescue of the tumor development phenotype." (PMID 32840881, 2021). "The current study explored the contributions of the lncRNA MCM3AP-AS1 in tumor-associated inflammation and angiogenesis in ccRCC with a specific focus on its transcriptional regulation and its interactions with transcription factor E2F1 and DPP4." (PMID 32714856, 2020). "Increased expression of E2F1 has been associated with DNA damage and tumor development." (PMID 33261027, 2020). "In addition, E2F1 is closely associated with AR function, both as an oncogene and a tumor suppressor." (PMID 32354165, 2020). "Also, univariate analysis indicated that higher E2F1 activity is significantly associated with advanced tumor stages (p < 0.01)." (PMID 30813560, 2019). "This was associated with the increased expression of the E2F1 protein only in tumor tissue specimens obtained from those patients harboring three copies of E2F1, whilst surrounding non tumor-tissue showed both lower E2F1 protein expression and downstream-mTOR phosphorylation." (PMID 31338064, 2019). "A compound can induce apoptosis in tumor cells through several mechanisms, such as blocking the cell cycle, inhibiting the phosphorylation of Bcl-2 and Bcl-xl, activating caspases, up-regulating E2F1, and causing the release of cytochrome c." (PMID 30002625, 2018). "Emerging evidence from in vitro human tumor analysis and transgenic mouse models indicates that G1/S-related cell cycle proteins, particularly cyclin E, p27, Rb, and E2F1, drive molecular mechanisms that underlie corticotroph-specific differentiation and development of Cushing disease." (PMID 30147673, 2018). "Moreover, the single nucleotide polymorphism (SNP) located in the mature region of miR-34a was highly associated with a decreased risk of CRC by regulation of 3’-UTR in tumor-promoting gene E2F transcription factor 1 (E2F1)." (PMID 30227605, 2018). "MIAs can induce apoptosis in tumor cells through several mechanisms, such as blocking the cell cycle, inhibiting the phosphorylation of Bcl-2 and Bcl-xl, activating caspases, upregulating E2F1, and causing the release of cytochrome c." (PMID 29069746, 2017). "Since RB1 loss is frequently observed in CRPC, the RB1/E2F-1 complex could play a significant role in tumor progression." (PMID 28264478, 2017). "There was significant interaction between the site of the tumor (colon vs. rectum) and the E2F1+TS+ immunophenotype with regard to an association with OS (P = 0.047) but significance of interaction was not achieved with regard to DFS (P = 0.15) in multivariate analysis." (PMID 26831819, 2016). "Furthermore, loss of E2F1 increased HPV-positive oral tumor growth that was associated with increased tumor cell proliferation." (PMID 26670255, 2015). "There was a significant delay in tumor latency associate with E2F1, E2F2 and E2F3 loss." (PMID 26682278, 2015). "E2F1 mRNA levels were significantly associated with tumor diameter(p=0.001) (r=0.265, p=0.011), Fuhrman tumor grade(p=0.001) (r=-0.366, p<0.001), pTstage(p=0.003) (r=-0.330, p=0.001), TNM stage grouping(p=0.001) (r=-0.363, p<0.001) and MAVI(p=0.001) (r=-0.377, p<0.001), but not age and sex." (PMID 24023875, 2013). "E2F1-/- mice can grow to maturity and reproduce normally but display a predisposition to develop various cancers, indicating the greater importance of the tumor suppressive function of E2F1 compared to its cell cycle gene activation function." (PMID 21955916, 2011). "Moreover, the roles of E2F-1 in cancer have been well-recognized due to its association with pRB1— a classic tumor suppressor." (PMID 20976175, 2010).
tumor (continued). "In addition, E2F1 overexpression was tightly linked to tumor grade and TNM stages." (PMID 34699320, 2021). "However, a higher E2F1 expression level was correlated with a higher risk of tumor recurrence in male GC patients, suggesting that E2F1 can serve as a predictive biomarker for tumor recurrence risk in male GC patients." (PMID 33986804, 2021). "Therefore, studies with larger patient samples may be needed to further confirm the potential value of E2F1 in predicting the risk of tumor recurrence in GC patients." (PMID 33986804, 2021). "It has recently been shown that the E2F1 and FoxO1 transcription factors physically associate to control expression of the pro-apoptotic Apaf1 gene in vitro, but the effects of this complex in suppressing tumor onset in vivo is completely unknown." (PMID 25907958, 2015). "Furthermore, only loss of E2f1 significantly reduced tumor development in Rb;p107 deficient mice." (PMID 25338120, 2014). "Methylated E2F1 regulates genes that are responsible for prostate gland development, tumor suppression, and negative regulation of cell migration, while unmethylated E2F1 promotes cell proliferation and negative regulation of apoptosis." (PMID 41540805, 2026). "Given the ubiquitous and high basal expression of G6PD in both tumor and normal gastric tissues, establishing a clear regulatory link between E2F1 and G6PD in patient-derived samples is technically challenging." (PMID 41484982, 2026). "It promotes tumor proliferation and invasion by activating the transcription factor E2F1, making it a potential prognostic marker and therapeutic target." (PMID 41564103, 2026). "In summary, RRBP1 drives tumor malignant progression in high glucose environments through the E2F1/RRBP1 signaling axis and E2F1 directly binds RRBP1, and enhances its transcriptional activity, thereby promoting HCC cell proliferation, migration and invasion." (PMID 41200062, 2026). "Among activator E2Fs, E2F1 has the highest ability to activate pro-apoptotic genes and plays a central role in E2F-mediated tumor suppression." (PMID 41511373, 2026). "E2F1 has important functions including DNA replication, checkpoint response and DNA repair in the cell cycle process in tumor cells, which has been widely reported in many studies." (PMID 41050059, 2025). "Cell experiments also showed that overexpression of E2F1 inhibited the invasion, proliferation, and migration of tumor cells." (PMID 41050059, 2025). "According to previous research, Fouad S demonstrated E2F1 as a transcription factor for tumor advanced development." (PMID 40886002, 2025). "MiR-326 exerts its tumor-suppressive effects by targeting E2F1, a transcription factor involved in cell proliferation and survival, thereby inhibiting cancer cell viability and metastatic potential." (PMID 40227597, 2025). "Collectively, our findings suggest that immune pressure induced by immunotherapy drives the selection of E2F1+ tumor cells, which subsequently upregulate HMGCR expression and contribute to ferroptosis resistance." (PMID 41339438, 2025). "Overexpression of CDK1 mRNA and protein has been frequently observed in tumor tissues, potentially driven by gene amplification or activation of upstream transcriptional regulators such as E2F1 and FOXM1." (PMID 41009727, 2025). "Supporting the role of E2F1 in apoptosis and tumor suppression, in vivo studies demonstrate that E2F1 homozygous knockout mice spontaneously develop tumors, and thymocytes from these mice are resistant to apoptosis." (PMID 40517236, 2025).
tumor (continued). "E2F1-driven senescence also reshapes the tumor microenvironment via the SASP to limit metastatic potential." (PMID 41050059, 2025). "Clinical data reveal a significant correlation between E2F1 expression and stemness marker expression, as well as its role in promoting tumor metastasis progression." (PMID 40886002, 2025). "In our cellular experiments, we found that the overexpression of E2F1 inhibited tumor cell invasion, migration, activity, and colony formation." (PMID 41050059, 2025). "Regarding prognosis, E2F1 expression was associated with age, gender, smoking, stage, and tumor size, whereas MYC correlated with smoking, tumor size, and metastasis, and SOX2 was only associated with lymph node metastasis." (PMID 40886002, 2025). "Given an essential role of ferroptosis in the anti-tumor immunity induced by T cell-based therapies, our finding provides a strong rationale that the E2F1-HMGCR axis can be used to predict the clinical outcomes of ICB therapy." (PMID 41339438, 2025). "Building upon previous findings, we further establish E2F1 as a key regulator of both apoptosis and ferroptosis resistance in the context of tumor cell death mediated by CTLs reinvigorated through anti-PD1 therapy." (PMID 41339438, 2025). "Further, RNA-seq of BT549 cells after siKNSTRN revealed pronounced downregulation of critical cell cycle-related genes, including CDK2, CDC20, FOXM1, and E2F1, which have been documented to drive uncontrolled proliferation and tumor growth in TNBC." (PMID 41209020, 2025). "In this context, the DDX5 gene targeted by deregulated E2F1, would form a positive feed forward loop mechanism contributing to E2F1-mediated tumor suppression." (PMID 40869977, 2025). "The findings demonstrate that CCNA2, CHK1, E2F1, and TOP2A exhibit significant associations with tumor stage and size, whereas CHK2 shows a correlation solely with age." (PMID 40573296, 2025). "A key finding of this study is the potential direct transcriptional regulation of STMN1 by E2F1 and the correlation between STMN1 expression and RB1 loss, a critical tumor suppressor in PCa." (PMID 39776361, 2025). "Consistent with this, scratch assay results demonstrated that E2F1 knockdown significantly increased the colony formation capacity of tumor cells (p < 0.05)." (PMID 41050059, 2025). "E2F1 inhibition results in the activation of transcription of endogenous retroviral elements in tumor cells and in triggering the interferon pathway as a response to the presence of cytoplasmic double-strand RNA." (PMID 40699853, 2025). "Network modeling and gene expression profiling have identified tumor-specific receptor signatures in which high E2F1, TGFBR1, and FGFR1 activity fosters invasive phenotypes." (PMID 40299510, 2025). "The PCR results revealed that E2F1 expression was higher in tumor cells compared to normal cells, with the expression level in K1 cells being higher than that in TPC-1 cells." (PMID 41050059, 2025). "The other four (EPAS1, MXI1, ARNT2, and E2F1) relate to the signaling pathways involved in the processes of tumor formation and development." (PMID 40724805, 2025). "For example, tumour cells exhibited high activity of regulons regulated by TFs such as GATA2, NFIL3 and E2F1, which are associated with cell proliferation and survival." (PMID 40099956, 2025). "E2F1 regulates both cell cycle and apoptosis, and its activity is often deregulated in human tumours." (PMID 40773523, 2025). "We also observed significant deregulation of the transcriptional landscape and cytokine secretion of CD8+ T cells depending on tumor-intrinsic E2F1 levels." (PMID 40299510, 2025). "Meanwhile, the paired t-test between the PTC tissue and its adjacent normal thyroid tissues also indicated the expression of E2F1 was higher in the tumor than in adjacent normal thyroid tissues." (PMID 41050059, 2025). "Meanwhile, the serum levels of E2F1 also positively correlated with tumor stage (P = 0.030) and distant metastasis (P = 0.020)." (PMID 40886002, 2025).
tumor (continued). "The conclusions of this study are as follows.Rab proteins (i.e., Rab9 and Rab42) promote tumour progression by influencing trafficking and interacting with other proteins and pathways (e.g., p40, E2F1, immune tolerance, and checkpoint proteins)." (PMID 40293576, 2025). "E2F1 is the most classical member of the E2F family and plays a multifaceted role in regulating tumor development by targeting various signaling pathways, including the Wnt/β-catenin pathway 34, the Notch pathway 35, and the PI3K/AKT/mTOR pathway." (PMID 39991770, 2025). "Researchers demonstrated that the formation of the SLNCR1–E2F1 complex guides E2F1 to activate genes, promoting tumour progression." (PMID 41463281, 2025). "Tumor-selectivity is mediated by the E2F-1 promoter-controlled virus replication in Rb-pathway defective tumor cells." (PMID 41445946, 2025). "miR-187-5p is downregulated by HBx in HBV-related HCC and inhibits tumor cell proliferation by targeting the E2F1/FoxP3 axis." (PMID 40625740, 2025). "E2F1 can inhibit the development of malignant tumor phenotypes by regulating cellular senescence, thereby reducing the risk of poor prognosis." (PMID 41050059, 2025). "Senescence-associated markers were examined by Western blot analysis, while flow cytometry was employed to evaluate cell viability, thereby delineating the impact of E2F1 on tumor cell senescence." (PMID 41050059, 2025). "Further, there was a highly significant correlation between an amplified MYCN gene, and levels of PRMT5 and E2F1 gene expression in the tumour tissue." (PMID 39021294, 2025). "By identifying the E2F1–HMGCR axis as a key driver of this resistance, we demonstrate that HMGCR inhibition restores ferroptosis sensitivity, rendering immune-refractory tumor cells susceptible to ACT and PD-1 blockade." (PMID 41339438, 2025). "E2F7 promotes the proliferation, motility, and invasion of CRC cells and enhances the functionality of CRC tumor stem cells, while E2F1 exhibits tumor-suppressive functions in CRC." (PMID 40842994, 2025). "This association was functionally supported by xenograft tumorigenesis experiments in nude mice, where E2F1-driven tumors exhibited stronger tumorigenicity, enhanced stemness, and tumor growth-promoting characteristics." (PMID 40886002, 2025). "Mechanistically, this synergy involves the downregulation of key oncogenic transcripts, c-Myc and E2F1, leading to suppressed tumor growth." (PMID 41281757, 2025). "Studies have shown that E2F1 can act both as a promoter of cell proliferation and an inhibitor of apoptosis, playing a dual role in tumor progression." (PMID 40661777, 2025). "Morris and colleagues initially noted that the depletion of API5 was specifically lethal to tumor cells with deregulated E2F1." (PMID 38275765, 2024). "The public database analysis revealed that transcription levels of E2F1-8 in tumor tissues were higher than those in normal tissues." (PMID 38371373, 2024). "These signaling pathways can then directly induce MYC activity and subsequently stimulate the activity of critical nuclear factors that govern tumor migration and invasion, of which the activity of E2F1, CDK4, p27, and p15 stands out." (PMID 38204280, 2024). "In the early stage of tumors, E2F1 promotes both cell proliferation and apoptosis and has been shown to delay tumor progression." (PMID 38827325, 2024). "Taken together, these results suggest that the N-terminal region of E2F1 contains a novel transactivation domain that mediates the activation of tumor suppressor genes, at least in part, by recruiting GTF2H2." (PMID 39595534, 2024).
tumor (continued). "A helicase defective mutant DDX5(K144R) resulted in similarly enhanced E2F1-mediated activation of tumor suppressor genes compared to wild-type DDX5, suggesting that DDX5 coactivator function is independent of its helicase activity." (PMID 39769018, 2024). "Kaplan‒Meier tumor-free curves showed that although the MYBL2-knockdown group presented the latest tumor onset, the mice with E2F1 overexpression and MYBL2 knockdown appeared to have later tumor onset than those with E2F1 overexpression alone." (PMID 39613162, 2024). "MYBL2 and RAD54L have been demonstrated to be downstream targets of E2F1, which has been demonstrated to be involved in tumor growth and metastasis." (PMID 38424195, 2024). "DNA methylation of E2F1 has been associated with clinical outcomes in distinct subtypes of AML51, although E2F1 has been proposed to be both oncogene and tumor suppressors in cancer." (PMID 38594351, 2024). "As the pRb pathway is inactive in many tumor cells, this can lead to the dysregulation of E2F1 activity, resulting in uncontrolled cell proliferation." (PMID 38275765, 2024). "E2F1, an extensively studied transcription factor, mediates multiple malignant behaviors by regulating cell cycle progression, tumor metastasis, and therapeutic response." (PMID 39119602, 2024). "Using transcriptomic profiling, bioinformatic analyses, and structural modeling, we found that E2F1 orchestrates the tumor niche by activating an IL6-based gene regulatory network (GRN) and a highly inflammatory secretome." (PMID 39544930, 2024). "Z Lu, RZ Luo, H Peng, M Huang, A Nishmoto, KK Hunt, K Helin, WS Liao and Y Yu reported that E2F1 negatively regulates tumor suppressor genes in breast cancer." (PMID 38783241, 2024). "Taken together, the data from the tumor xenografts support that E2F1 and E2F7 transcriptionally activate and repress MYBL2 to promote and inhibit GC cell proliferation, respectively." (PMID 39613162, 2024). "Emerging evidence has demonstrated that lncRNAs contribute to E2F1 pathway regulation and play multifaceted roles in the disease progression in diverse tumor types." (PMID 39119602, 2024). "Transcription factor E2F1 regulates sphingosine kinase 1 (SPHK1), which is known to promote angiogenesis, and a contribution of HULC/E2F1/SPHK1 axis in augmenting tumor angiogenesis was shown." (PMID 38203767, 2024). "In line with above results, the WB analysis in tumor tissues of mice suggested that the protein levels of FOXM1 and E2F1 were significantly upregulated in CDCA5-overexpressiong tumor tissues." (PMID 38978058, 2024). "Although E2F1 overexpression significantly increased tumor volume, tumor weight, and tumor growth, these effects were attenuated by MYBL2 knockdown." (PMID 39613162, 2024). "The transcription factor E2F1, the principal target of pRB, plays crucial roles in cell proliferation and tumor suppression, and regulates other cellular processes such as differentiation, DNA damage response, apoptosis, and metabolism." (PMID 39769018, 2024). "We thus examined the roles of the N-terminal region of E2F1 in the regulation of tumor suppressor genes in relation to GTF2H2." (PMID 39595534, 2024). "We show here that the N-terminal region of E2F1 is critical for the activation of tumor suppressor genes." (PMID 39595534, 2024). "Higher E2F1/E2F7 mRNA ratios were correlated with poor prognosis, whereas higher E2F7/E2F1 mRNA ratios were correlated with good prognosis, further supporting the oncogenic role of E2F1 and the tumor suppressor role of E2F7 in GC." (PMID 39613162, 2024).